LARP7 (La ribonucleoprotein 7, transcriptional regulator)
Diseases named in the same sentence as LARP7 in open-access papers (continued):
Sharing a sentence is not in itself a finding about the gene and the disease.
microcephaly (2 papers, 2022 to 2025). A congenital or acquired developmental disorder in which the circumference of the head is smaller than normal for the person's age and sex. "Knockdown of LARP7 showed reduction of neuronal ribosome content as well as inhibition of protein synthesis in the hippocampal neurons; mutations in LARP7 are linked to microcephaly." (PMID 35371036, 2022).
bladder cancer (1 paper, 2016). "Our current studies indicated that p100 could increase LARP7 transcription, which hosts miR-302d in the intron, and p100-mediated activation of miR-302d expression was crucial for its suppression of Cyclin D1 protein translation in bladder cancer cells." (PMID 27095572, 2016).
epilepsy (1 paper, 2021). A brain disorder characterized by episodes of abnormally increased neuronal discharge resulting in transient episodes of sensory or motor neurological dysfunction, or psychic dysfunction. "The last two genes were newly discovered neurodevelopmental syndrome genes (LARP7 and YY1), which require more cases to summarize clinical characteristics and to update the epilepsy-associated gene lists." (PMID 34992632, 2021).
HIV-1 infection (1 paper, 2025). The type species of lentivirus and the etiologic agent of acquired immunodeficiency syndrome (AIDS). "HIV-1 infection induces liquid-liquid phase separation of LARP7, forming condensates that sequester Tat and P-TEFb to inhibit viral transcription." (PMID 40113991, 2025). "Here, we report that HIV-1 infection triggers liquid-liquid phase separation of LARP7, a central component of 7SK snRNP." (PMID 40113991, 2025). "In this study, we discovered that HIV-1 infection enhances the LLPS of LARP7." (PMID 40113991, 2025).
Hyperhidrosis (1 paper, 2020). Abnormal excessive perspiration (sweating) despite the lack of appropriate stimuli like hot and humid weather. "Nevertheless, at the moment, we cannot exclude that acrocyanosis and palmoplantar hyperhidrosis might represent unusual phenotypic manifestations of LARP7, OTOG, or a combination of both." (PMID 32244554, 2020). "This patient also presented acrocyanosis and palmoplantar hyperhidrosis, which might represent unusual phenotypic manifestations of LARP7, OTOG, or a combination of both." (PMID 32244554, 2020).
invasive breast carcinoma (1 paper, 2014). A carcinoma that infiltrates the breast parenchyma. "Consistent with the demonstration that LARP7 is necessary for the integrity of the 7SK snRNA, the reduced LARP7 expression in invasive breast cancer cell lines was accompanied by a decrease in 7SK snRNA." (PMID 25053741, 2014).
melanoma (1 paper, 2021). A malignant, usually aggressive tumor composed of atypical, neoplastic melanocytes. "In the zebrafish melanoma model study, it was found that knockout LARP7 could rescue melanocyte gene expression and observe melanocytes in knockout HEXIM1." (PMID 34107850, 2021).
myocardial infarction (1 paper, 2025). Gross necrosis of the myocardium, as a result of interruption of the blood supply to the area, as in coronary thrombosis. "Using inhibitors of ATM, such as KU60019, ultimately restored levels of LARP7, SIRT1 and mitochondrial biogenesis preventing adverse remodeling effects of myocardial infarction (MI)." (PMID 40264508, 2025).
pancreatic cancer (1 paper, 2022). "In the pancreatic cancer tissues, we confirmed that protein levels of LARP7, CDK1, and CCNB1 increased notably in tumor tissues compared with non-tumor tissues." (PMID 36434634, 2022). "Therefore, the decreased expression of HOGA1 might be a diagnostic indicator of PDAC, and inhibiting LARP7, which collaborated with HOGA1, would provide another feasible strategy for suppressing pancreatic cancer development in clinic." (PMID 36434634, 2022).
vitiligo (1 paper, 2021). Generalized well circumscribed patches of leukoderma that are generally distributed over symmetric body locations and is due to autoimmune destruction of melanocytes. "Ultimately, TYR, TYRP1, DCT, and LARP7 have been screened as candidate biomarkers associated with vitiligo." (PMID 34107850, 2021). "TYR, TYRP1, DCT, and LARP7 were selected as biomarkers associated with vitiligo." (PMID 34107850, 2021). "In summary, we found that TYR, TYRP1, DCT, and LARP7 are biomarkers associated with vitiligo." (PMID 34107850, 2021). "Herein, TYR, TYRP1, DCT, and LARP7 were chosen as biomarkers to identify vitiligo by combining machine learning algorithm and WGCNA." (PMID 34107850, 2021). "TYR, TYRP1, DCT, and LARP7 were involved in the pathogenesis of vitiligo." (PMID 34107850, 2021). "TYR, TYRP1, DCT and LARP7 were identified as vitiligo-related biomarkers." (PMID 34107850, 2021).
cancer (12 papers, 2009 to 2024). A tumor composed of atypical neoplastic, often pleomorphic cells that invade other tissues. "Patients with Alazami syndrome exhibit very short telomeres, and LARP7 knockdown in cancer cells causes a reduction in telomerase activity and telomere shortening." (PMID 39009594, 2024). "Of the LARPs, La, LARP1 and LARP7 have also been implicated in cancer, albeit with rather distinct mechanisms." (PMID 27615744, 2016). "Depletion of LARP7 caused a reduction in telomerase enzymatic activity and progressively shorter telomeres in human cancer cell lines." (PMID 27766953, 2016). "In contrast to La and LARP1, LARP7 is lost or mutated in a number of cancers." (PMID 27615744, 2016). "Since EMT has recently been linked to the expansion of cancer stem cells (CSCs), we also examined whether the LARP7 KD cells displayed an increased CSC feature in the two-round mammosphere formation assay." (PMID 25053741, 2014). "The role of LARP7 in cancer remains controversial, as it functions either an activator or suppressor in cancer, but its impact on NB remains undocumented." (PMID 39175876, 2024). "This analysis focused on the functionally significant components of the multimeric RNAPII complex, including BRD4, HEXIM1, Spt5, NELF-A, Cyclin T, CDK9, LARP-7, and Caspase-8, which collectively serve as a regulatory hub in gene expression in cancer cells." (PMID 38201534, 2023). "For example, LARP7 downregulation has been confirmed in several cancers, which subsequently potentiates CDK9-mediated transcription elongation and promotes cancer growth and metastasis." (PMID 35088192, 2023). "At the center of network 1 lies LARP7, a transcription regulator whose expression levels play a role in cancer progression and metastasis." (PMID 35216124, 2022). "As emerging research uncovers the function of each LARP, it is evident that La, LARP1, LARP6, LARP7 and possibly LARP4a and 4b are dysregulated in cancer." (PMID 26501340, 2015). "Statistical analysis revealed that downregulation of LARP7 correlated with features of advanced cancer progression including estrogen receptor (ER) status, tumor size, and metastasis." (PMID 25053741, 2014). "Down-regulation of Hexim1 and/or LARP7 in breast and cervical cancer most likely leads to increase of free-pool P-TEFb and consequent activation of cancer-related genes." (PMID 19723344, 2009). "Interestingly, its C-terminus is often deleted in human tumors suggesting that activation of P-TEFb mediated by LARP7 destabilization of large complex is important for proliferation and tumorigenicity of cancer cells." (PMID 19723344, 2009). "Interestingly, expression of LARP7 protein is lost from tumour tissue during cancer progression." (PMID 26501340, 2015). "Emerging evidence suggests that some CDK9-related negative regulators (e.g., HEXIM 1/2, LARP7, and MePCE) are also involved in CDK9-related diseases, e.g., cancers." (PMID 35088192, 2023).
tumor (8 papers, 2014 to 2025). "This makes the missense mutation rs79383654 (Glu4Lys), affecting LARP7, a likely candidate factor influencing the enrichment of G4 strong context around the points of somatic mutations in tumor cells of patients with MM." (PMID 38791307, 2024). "Targeting LARP7 was able to intercept the tumor-promoting effect of HOGA1 loss and avoid affecting glyoxylate metabolism." (PMID 36434634, 2022). "La, LARP1 and LARP6 are upregulated and associated with tumour invasion and migration whereas LARP7 and possibly LARP4a are down-regulated in malignancy and associated with progression and metastasis." (PMID 26501340, 2015). "In contrast, cells expressing the Δ2A mutant formed as many colonies as the vector control cells, suggesting that the ability of LARP7 to assemble 7SK snRNP and suppress P-TEFb is necessary for its tumor suppressor potential." (PMID 25053741, 2014). "Because LARP7 is a critical component of the inhibitory 7SK snRNP, we hypothesize that its ability to suppress tumor progression is due to the sequestration of P-TEFb in 7SK snRNP." (PMID 25053741, 2014). "The expression of the La ribonucleoprotein domain family member 7 (LARP7), regulating telomerase activity, decreased over 120-fold following long-term tumor hVDAC1 depletion." (PMID 31661894, 2019). "This function of LARP7 is additionally supported by the observation that the Drosophila homolog of LARP7, multisex-combs (MXC), also acts as a tumor suppressor to inhibit cell growth." (PMID 25053741, 2014). "In addition, we noted that loss of HOGA1 expression promoted the xenograft growth of PANC-1 cells, whereas knockdown of LARP7 abrogated the effect of HOGA1 and delayed the xenograft growth of tumor cells." (PMID 36434634, 2022). "More recently, short hairpin silencing of LARP7 in MCF10A cells has been shown to upregulate the P-TEFb mediated expression of EMT and metastasis genes (such as Slug, ZEB2 and Twist1) resulting in enhanced tumour progression and metastasis." (PMID 26501340, 2015).
infection (2 papers, 2019 to 2025). The state of being infected such as from the introduction of a foreign agent such as serum, vaccine, antigenic substance or organism. "The range of pathogenic effectors that modulate host transcription machinery is limited, and the manipulation of the host 7SK snRNP complex via LARP7-AnkH interaction identifies a novel effector mechanism for host transcription control during infection." (PMID 31455655, 2019). "Tat is incorporated into HIV-1-induced LARP7 condensates after infection." (PMID 40113991, 2025).
bacterial infection (1 paper, 2019). "LARP7 knockdown partially suppresses intracellular proliferation of wild-type (WT) bacteria and increases the severity of the defect of the ΔankH mutant, indicating a role for LARP7 in permissiveness of host cells to intracellular bacterial infection." (PMID 31455655, 2019).
cardiovascular diseases (1 paper, 2024). "Our study also suggested a translational potential of Larp7 overexpression in preventing ageing and cardiovascular diseases." (PMID 38818612, 2024). "Our previous studies have shown that Larp7 serves as a novel activator of Sirt1 deacetylase and plays a protective role in age‐related disorders and cardiovascular diseases." (PMID 38818612, 2024).
gastrointestinal tumors (1 paper, 2021). "La ribonucleoprotein domain family, member-7 (LARP7), belongs to LARP RNA binding protein family and is BRCA1 ubiquitinase substrate regulating the metabolism and function of many RNA species and inhibit the occurrence of gastrointestinal tumors." (PMID 34107850, 2021).
LARP7 also shares sentences with these, for which no sentence is quoted: developmental delay (3 papers); Primordial Dwarfism (2); anemia (1); autism (1); benign tumors (1); Cognitive impairment (1); deafness (1); diabetic nephropathy (1); ductal carcinoma in situ (1); dyskeratosis congenita (1); Failure to thrive (1); invasive carcinoma (1); invasive ductal carcinoma (1); Legionella infection (1); metastatic cancer (1); neurodevelopmental disorder (1); neurosensorial deafness (1); premature ageing syndromes (1).